LAMB1 (laminin subunit beta 1)
Diseases named in the same sentence as LAMB1 in open-access papers (continued):
Sharing a sentence is not in itself a finding about the gene and the disease.
small cell lung carcinoma (1 paper, 2013). Small cell lung cancer (SCLC) is a highly aggressive malignant neoplasm, accounting for 10-15% of lung cancer cases, characterized byrapid growth, and early metastasis. "For example, in the Small cell lung cancer there is a long chain of regulations connecting the ECM-receptor LAMB1 and TRAF1 which is represented by a directed edge in BNKL - inhibition in the first class (red tee arrowhead) and activation in the second (blue arrowhead)." (PMID 24565081, 2013).
viral infection (1 paper, 2025). "However, research on the function of C3 and LAMB1 in viral infection is fairly limited." (PMID 40237496, 2025).
tumor (43 papers, 2015 to 2025). "High expression of LAMB1 is significantly associated with an immune-suppressive tumor microenvironment in NPC." (PMID 39874810, 2025). "LAMA4 and LAMB1 might be associated with tumor purity in OC." (PMID 34512203, 2021). "CD9+/CD63+/CD81+ EVs (Transport‐EVs) transmit resistance, whereas CD147+/LAMB1+ EVs (Excretion‐EVs) excrete tumour‐suppressive cargos, highlighting the functional divergence of EV subtypes in GCB resistance." (PMID 41159684, 2025). "Meanwhile, the LAMB1 expression level was correlated with the expression of tumor immune infiltration, immune checkpoints, and T cell effectors, indicating the immunomodulatory biomarker potential of LAMB1." (PMID 39312319, 2024). "Gene set enrichment analysis and CIBERSORT analyses revealed that LAMB1 expression correlated with tumor immune microenvironment." (PMID 39312319, 2024). "The interaction pairs via SPP1, RARRES2, NECTIN3, LGALS9, and LAMB1 showed increased signaling in the autophagy-high tumor cells, while SEMA3C, PTN, ICAM1, GAS6, and CSF1 showed decreased signaling compared with those in the autophagy-low tumor cells." (PMID 36830707, 2023). "It has been reported that LAMB1 overexpressed in several types of tumors and correlated with tumor metastasis and poor prognosis." (PMID 36494846, 2022). "Our analysis shows that upregulation of LAMC1 and LAMB1 gene expression is a marker of poor prognosis for certain tumours." (PMID 34158478, 2021). "Since LamB1 plays important role in the regulation of cell migration, increased IRES-dependent translation of LamB1 during EMT contributes to tumor cell migration and metastasis." (PMID 32517298, 2020). "As part of a subunit which assembles to a heterotrimeric isoform, Lamb1 facilitates cell differentiation, motility, adhesion and—as a ligand of the laminin receptor—it enables the ability of tumor cells to invade and build vessels." (PMID 31739488, 2019). "These canonical EVs may function in tandem with CD147+ or LAMB1+ EVs, either by facilitating resistance transfer or by compensatory excretion of tumour‐suppressive cargos." (PMID 41159684, 2025). "The role of LAMB1 in basement membranes and tumour‐derived sEVs may be related to communication between PCa cells and the TME." (PMID 38590132, 2024). "Finally, multicentric studies are required to validate the tumor-promoting or suppressing effects of the LAMB1 gene." (PMID 39312319, 2024). "A specific EV subpopulation enriched in CD147 and LAMB1—referred to as Excretion EVs—carried H3.2 (H3C14) but did not induce GCB resistance in recipient cells, suggesting their primary role in eliminating proteins associated with tumour progression and drug resistance." (PMID 41159684, 2025). "Cell Adhesion and Migration: CD44, ITGB1, LAMB1, FAT1, PLAUR, and TGFBI are integral to cell–matrix interactions and extracellular matrix (ECM) remodeling, processes critical for tumor invasion and metastasis." (PMID 41303451, 2025). "High expression of LAMB1 promoted the progression of NPC by inhibiting immune responses and enhancing the malignant nature of tumor cells." (PMID 39874810, 2025). "The identification of Excretion‐EVs as carriers of tumour‐suppressive proteins, such as H3.2 (H3C14), CD147 and LAMB1, highlights an underexplored mechanism of GCB resistance involving the active excretion of unwanted intracellular regulators via EV secretion." (PMID 41159684, 2025). "Additionally, laminin encoded by LAMA4, LAMB1, and LAMB2 mediate adhesion through Integrin binding—specifically the Integrin α6β4, composed of integrin α6 (ITGA6) and Integrin β4 (ITGB4)—is suggested to be essential for tumor development and progression, promoting pro-cancer signaling pathways." (PMID 40333631, 2025). "We also examined the expression of LAMB1 and NID1 in human pNF tumor samples and found that both were abundantly deposited in human pNF samples compared with normal sciatic nerve." (PMID 37140985, 2023).
tumor (continued). "Here, we demonstrate the tumour cell-specific expression of laminin chains α5, β1 and γ1 (LAMA5, LAMB1 and LAMC1 respectively) in orthotopic human liver metastases from mice and the deposition of these laminin chains within the tumour stroma." (PMID 31064120, 2019). "In low tumor Hp expression group, TWIST1 (r = -0.54, p < 0.01), LAMB1 (r = -0.58, p < 0.001), and THY1 (r = -0.48, p < 0.01) showed negative correlation with Hp." (PMID 28158312, 2017). "Additionally, we observed that the expressions of the cell adhesion-related genes FN1 and LAMB1 were upregulated after PAQR3 knockdown, aligning with the biological function of PAQR3 as a tumor suppressor gene." (PMID 40723340, 2025). "Targeting EV biogenesis or sorting mechanisms such as Rab27A inhibition or the interactions between CD63, LAMB1 and CD147 could provide novel therapeutic avenues to reverse resistance and re‐sensitize tumours to GCB." (PMID 41159684, 2025). "LAMB1 is the major non-collagenous component of Extracellular Matrix (ECM) and implicated in tumor metastasis as well as poor prognosis in several cancers." (PMID 39874810, 2025). "Additionally, LAMB1 was under-expressed in SCLC and LCC but overexpressed in SqCC, and it also showed significant differences between SqCC and all other tumor tissues." (PMID 35681609, 2022). "The ROC analysis of the laminins in OC datasets showed that the LAMA2/A4/A5, LAMB1/B2/B3, and LAMC2 mRNA levels could be considered to effectively differentiate between malignant tumor and non-tumor tissues." (PMID 34512203, 2021). "Genes encoding collagens (COL4A1, COL4A2), collagen-modifying enzyme (PXDN), and other components of the basement membrane (LAMB1, HSPG2) also ranked in the top 10 most enriched Co1 EC markers, indicating that extensive matrix remodeling occurs in GBM during tumor angiogenesis." (PMID 34228647, 2021). "Human LAMA5, LAMB1 and LAMC1 transcripts were identified in orthotopic metastases, a finding supported by immunohistochemical analysis demonstrating the expression of the human LAMA5 protein in these tumours." (PMID 31064120, 2019). "In addition, silencing of PLA2G7, RHOU, ACSM1, LAMB1 and CACNA1D also resulted in reduced tumor cell invasion in PC3 organoid cultures." (PMID 27196083, 2016). "Substantial differences between tumor and neighboring healthy cortex were found in both interstitial matrix proteins, such as collagen 6 (COL6A1, COL6A2, COL6A3), and basement membrane components such as collagen 4 (COL4A1, COL4A2) and laminins (LAMA5, LAMA4, LAMB1, LAMB2, LAMC1)." (PMID 34884982, 2021). "Furthermore, μ-21 could potentially inhibit tumor cell proliferation and reduce the immunosuppressiveness of the tumor microenvironment via regulation of microtubule component TUBB4B and the matrix protein LAMB1, respectively." (PMID 41373892, 2025). "Overall, the ROC analysis of the laminins in the OC sets indicated that LAMA2/A4/A5, LAMB1/B2/B3, and LAMC2 could be considered to accurately differentiate between tumor and non-tumor tissues." (PMID 34512203, 2021). "There were negative correlations between OC tumor purity and LAMA4 and LAMB1." (PMID 34512203, 2021). "Thus, the negative correlation of TWIST1 (r = -0.54, p < 0.01), LAMB1 (r = -0.58, p < 0.001), and THY1 (r = -0.48, p < 0.01) in low tumor Hp expression groups could be a signature of poor cancer differentiation also the prognostic role of Hp in HCC cancer cell differentiation." (PMID 28158312, 2017).
cancer (33 papers, 2012 to 2026). A tumor composed of atypical neoplastic, often pleomorphic cells that invade other tissues. "Laminin subunit Beta-1 (LAMB1), a component of the extracellular matrix, has been reported to be implicated in the development and progression of cancer." (PMID 39874810, 2025). "Laminin subunit beta 1 (LAMB1) is involved in attachment, migration, and organization during development, and its elevated expression has been associated with several cancers." (PMID 33435161, 2021). "Additionally, pan-cancer analysis showed abnormal expression and clinical outcome associations of LAMB1 and ITGA9 in multiple cancers." (PMID 32581652, 2020). "Second, cancer databases and bioinformatics have demonstrated a link between LAMB1 and LUAD-infiltrating immune cells." (PMID 39312319, 2024). "In this study, we first find LAMB1 plays a significant role in cancer cell communication and mediating PCa metastasis through sEVs." (PMID 38590132, 2024). "Pan-cancer analysis showed the correlation between abnormal expression of LAMB1 in various cancers and clinical outcomes." (PMID 38239636, 2023). "We explored the expression and prognosis of ITGA9 and LAMB1 mRNA in different cancers based on the Oncomine database and the PrognoScan database respectively." (PMID 32581652, 2020). "Here, we found that LAMB1 was abnormally expressed and was associated with OS and DSS in many cancers, which were consistent with previous results." (PMID 32581652, 2020). "Up-regulation of LAMB1 showed poor differentiation and aggressive cancer phenotypes such as migration and invasion." (PMID 28158312, 2017). "In-depth analysis of epithelial cells identified H19 + myoepithelial cells (H19 + myoEpC) as the dominant malignant subpopulation, enriched in ACCB compared to other cancers and characterized by high expression of oncogenic pathways and ligands such as LAMB1 and WNT6." (PMID 41761191, 2026). "Previous studies have linked both LAMB1 and CD147 to cancer metastasis and EV biogenesis." (PMID 41159684, 2025). "LAMB1 was found to be involved in pathways in cancer by KEGG analysis." (PMID 39866228, 2025). "Most of the current research on LAMB1 focuses on its role in cancer." (PMID 40237496, 2025). "In gastric cancer, LAMB1 enhances cancer cell growth and motility through the ERK/c-Jun pathway." (PMID 39874810, 2025). "Among the listed ECM genes, two types were noted, those that were low in mono-cultures and high in co-cultures (e.g. COL1A, FN, LAMA1, primarily fibroblast-derived) and those that were high in both mono- and co-cultures (e.g. LAMA5 and LAMB1, primarily cancer cell-derived)." (PMID 39011470, 2024). "We examined whether the rescue of LAMB1 expression can induce the proliferation, invasion, and migration of cancer cells." (PMID 33435161, 2021). "It has been reported that LAMB1 is highly expressed in several invasive cancers." (PMID 33435161, 2021). "Studies have shown that LAMB1 was shown to be a potential biomarker in some cancers." (PMID 32581652, 2020). "Research has indicated that LAMB1 may be a viable biomarker for certain types of cancer." (PMID 38239636, 2023). "However, little is known about the transcription factor or regulator of LAMB1 in cancer." (PMID 33435161, 2021). "The data also showed that LAMB1 was involved in pathways, including ECM signaling and adhension, which mediated cell motility and progression in cancer." (PMID 33435161, 2021). "For futher study, we found the positive correlation between LAMB1 and HIF-1 mRNA expression in a varity of cancers using GEPIA database (p = 0.00018, spearman correlation coefficient r = 0.038)." (PMID 32581652, 2020). "We identified several extracellular proteins as up‐regulated in invaded compared to noninvaded nerves (some of these were also seen in PNI compared to non‐PNI cancer), including laminins LAMA2, LAMB1, COL6A3, periostin (POST), nidogen 1 (NID1), and TNC." (PMID 30690892, 2019).
cancer (continued). "The six selected genes (TWIST1, LAMB1, THY1, EZH2, SALL4, and TCF3) are involved in cell differentiation, HCC cancer stem cells (CSCs) markers, and CSCs involved pathways." (PMID 28158312, 2017). "Meanwhile, other cell-cell adhesion-related molecules, such as laminins (LAMA4, LAMA5, LAMB1, LAMB2 and LAMC2) and integrins (ITGA5, ITGA5, ITGB5, ITGA11 and ITGBL1), are elevated in cancer tissues." (PMID 22905095, 2012). "Furthermore, cancer microenvironment- dn, MANALO hypoxia dn, ELVIDGE hypoxia dn genesets were significantly enriched in patients with low LAMB1 expression in the GSE2658." (PMID 32581652, 2020). "In contrast to LAMB1, THBS1 has previously been shown to play a role in SCC and other cancers." (PMID 31580518, 2019). "ROC analysis of laminins in OC sets revealed that LAMA2/A4/A5, LAMB1/B2/B3, and LAMC2 could be used to differentiate between malignant tumors and non-neoplastic tissues." (PMID 34512203, 2021).
infection (3 papers, 2011 to 2025). The state of being infected such as from the introduction of a foreign agent such as serum, vaccine, antigenic substance or organism. "An anti-LAMB1 antibody was used to capture LAMB1 from whole-cell lysates at 24 h post-infection, and an immunoblotting assay for C3 was performed on the pulled-down protein complexes." (PMID 40237496, 2025). "The results showed that both LAMB1 and C3 were upregulated within 24 h of infection." (PMID 40237496, 2025). "Fibronectin and vitronectin reproducibly inhibited infection in these experiments by up to 40%, whilst LAMB1, ICAM-1, VCAM-1 or heparan sulphate did not affect the efficiency of infection." (PMID 21573183, 2011). "The relative mRNA levels of p16, p21, LAMB1 (MDA-MB-231 cells do not express p16), and SASP components were significantly altered post-infection." (PMID 39342391, 2024).
kidney diseases (1 paper, 2024). "This highlights the potential for LAMB1 as a therapeutic target for certain kidney diseases." (PMID 39519211, 2024).
LAMB1 also shares sentences with these, for which no sentence is quoted: Dystonia (3 papers); coloboma (2); lung carcinoma (2); movement disorder (2); acute lymphoblastic leukemia (1); benign colon neoplasm (1); breast tumor (1); cervical cancer (1); chordoma (1); citrullinemia (1); depression (1); dystroglycanopathies (1); endothelial dysfunction (1); Ewing sarcoma (1); hydranencephaly (1); inflammatory bowel disease (1); leiomyoma (1); leukemia (1); lung disease (1); lymphoma (1); melanoma (1); metastatic prostate carcinoma (1); muscular dystrophies (1); nephrotic syndrome (1); open-angle glaucoma (1); osteosarcoma (1); Primary hemophagocytic lymphohistiocytosis (1); rheumatoid arthritis (1); Schwartz-Jampel syndrome (1); ulcerative colitis (1).